ENSG00000201701
Synonyms: LOC124900559
Gene: Small nucleolar RNA gene on chromosome 3 (32,037,526 to 32,037,653, forward strand). Ensembl gene ENSG00000201701.
Gene Ontology:
Biological process: RNA processing
Cellular component: nucleolus
Homologues: Paralogues in human: SNORA25 (91% identical), SNORA25B (84% identical).